ALB (albumin)
Diseases named in the same sentence as ALB in open-access papers (continued):
Sharing a sentence is not in itself a finding about the gene and the disease.
coagulopathy (continued). "We present a secondary analysis of our randomized clinical trial evaluating the effect of POC coagulopathy management and intraoperative administration of 5% albumin as primary resuscitative fluid during LuTx surgery on early lung allograft function, incidence of PGD, and 1-year survival." (PMID 36894877, 2023). "Dilutional coagulopathy occurs when the patients’ plasma is exchanged with albumin or saline." (PMID 37150798, 2023). "Albumin/globulin ratio, neutrophil count, lymphocyte percentage, aspartate transaminase, alanine transaminase, hemoglobin, platelet count, white blood cell count, neutrophil percentage, systolic and diastolic pressure were identified as major predictors to the occurrence of acute coagulopathy." (PMID 33249760, 2021). "Laboratory tests: Lower hemoglobin and hematocrit; higher RDW (14.8% vs. 13.4%, p < 0.001); more pronounced coagulopathy (prolonged PT and elevated INR, both p < 0.01); lower albumin (33.2 vs. 38.9 g/L, p < 0.001); and higher C-reactive protein." (PMID 41458518, 2025). "We observed significant differences in the levels of Myoglobin, Creatine kinase-MB, Fibrinogen, RBC, Total Protein, Albumin between patients with coagulopathy and non-patients, and ISS and death outcomes were also different." (PMID 40055771, 2025). "Our meta-analysis found that CLD patients with SIBO showed a small but significantly increased coagulopathy and lower albumin levels than those without SIBO." (PMID 39844931, 2025). "The patients with coagulopathy had persistent and lower albumin concentrations than the patients without coagulopathy." (PMID 33564286, 2021). "Significant decreased albumin level and higher blood urea nitrogen level were observed in non-overt DIC baseline; while the level of γ-glutamyl transpeptidase in overt DIC patients was significantly increased as compared to non-coagulopathy patients." (PMID 33564286, 2021). "Plasma exchange with plasma rather than albumin could also be effective in temporarily reducing levels of pathologic antibodies and providing some correction of the coagulopathy in terms of the hypofibrinogenemia." (PMID 36229799, 2022). "Comparison between the two groups revealed that the S/T, CLI, CRP, coagulation disorders, blood glucose, and blood lactate levels were significantly higher in the CLS group than in the non-CLS group (P < 0.05), while the albumin level was significantly lower in the CLS group (P < 0.05)." (PMID 40692798, 2025).
Allergy (63 papers, 2008 to 2025). An allergy is an immune response or reaction to substances that are usually not harmful. "The main side effects observed with FFP were allergic reactions, while the use of an albumin solution was associated with perioperative bleeding." (PMID 39390213, 2025). "As a result, there is a risk of spreading dangerous viruses, triggering allergies, and other adverse reactions, which limits the application of albumin in the treatment of chronic diseases such as T2DM." (PMID 36747238, 2023). "On the contrary, exogenous albumin infusion disrupts the nutritional balance of the body and increases the risk of adverse reactions, e.g., allergies." (PMID 36566186, 2022). "The protective mechanism of albumin is similar to that of antithrombin, but excessive use of albumin will increase the cost of hospitalization for patients, and albumin is an allogeneic source, which will increase the risk of allergy in patients." (PMID 34690703, 2021). "However, early adsorbents faced challenges such as thrombus formation due to dislodgement and exhibited poor biocompatibility, leading to complications like allergy, hypotension, severe platelet destruction and notable albumin loss." (PMID 39927254, 2025). "Chicken serum albumin (CSA) is a hen’s egg yolk allergen causing IgE-mediated allergy." (PMID 29895783, 2018). "The possibility of crossreaction between patients allergic to horse albumin (Equ c3) and dog, cat, or guinea pig albumin should be stressed Horse allergy may cause varying clinical symptoms, such as urticaria, angioedema, rhinitis, or respiratory distress, and the onset of symptoms may be delayed." (PMID 23283110, 2009). "The cow's milk allergen molecule and serum albumin allergen molecule sensitizations according to the status of cow's milk allergy." (PMID 40708118, 2025). "This study presents findings on serum albumin sensitizations, emphasizing Bos d 6 within the context of RM allergy, in a cohort of 70 children with CMA who underwent ALEX2 testing." (PMID 40708118, 2025). "Albumin-bound paclitaxel (hereinafter referred to as albumin paclitaxel) prepared using albumin nanotechnology can solve the patient’s allergy problem and improve the anti-tumor effect." (PMID 40292112, 2025). "Bovine serum albumin, a whey protein, plays a central role in CMA and has also been implicated in red meat (RM) allergy in certain patients." (PMID 40708118, 2025). "The 2S albumin allergen in turnip is highly cross-reactive, and it mediates allergic disease through IgE antibodies." (PMID 39399526, 2024). "We report a unique case of a 60-year-old male with a past medical history of allergy to human albumin, alcoholic cirrhosis, and esophageal varices, who was admitted due to multiple episodes of hematemesis." (PMID 36851100, 2023). "The described patient had a past history of allergy to human albumin; therefore, hypersensitivity to platelet external membrane glycoproteins in an atopic patient seems to be the possible etiology." (PMID 36851100, 2023). "In the group of 76 children aged 0–5 years with chronic symptoms of atopic dermatitis, allergy to 2S albumin was the most common and amounted to 25%." (PMID 36675318, 2023). "Accordingly, understanding the mechanisms of IgE-mediated allergy to albumin will be a prerequisite for the development of adequate and safe treatment strategies." (PMID 37928538, 2023). "In fact, some patients show gradual remission of allergy to bird serum albumin after cessation of contact with bird feathers." (PMID 37928538, 2023). "Albumin-bound paclitaxel (nab-paclitaxel) is a solvent-free albumin-bound form of paclitaxel, which not only solves the allergy problem of paclitaxel but also improves its therapeutic effect." (PMID 37270638, 2023). "Odd ratios (OR) for allergy when sensitized for the 7S/11S globulin and 2S albumin fraction of the respective food." (PMID 37007648, 2023).
Allergy (continued). "Yet, as serum albumin is a protein also found in milk, patients with confirmed horse serum albumin inhalation allergy should also avoid horse milk consumption." (PMID 35407012, 2022). "More than 70% of individuals with inflammatory bowel disease react to egg albumin, 60% of seasonal allergy patients have IgG antibodies to eggs and 13% of adults with seasonal allergy have IgG antibodies to eggs." (PMID 30736445, 2019). "In these patients, there is secondary chicken meat and egg yolk allergy due to a primary IgE sensitization to bird feathers with IgE recognition of chicken serum albumin (also known as alpha-livetin or Gal d 5) as an allergen." (PMID 28818076, 2017). "Another lipocalin allergen, Equ c 2, and a highly cross-reactive horse albumin, Equ c 3, were also described but likely play a minor role in horse allergy." (PMID 30402618, 2017). "In particular, increased IgE against the 2S-albumin Ara h 2 is a predictor for severe allergic reactions." (PMID 30402615, 2017). "Unfortunately, albumin administration still possibly contributes to allergies and viral or prion infections of the recipients." (PMID 26752241, 2016). "IgE cross-reactions within the serum albumin and lipocalin families, their implications for the diagnosis of allergies and their clinical relevance are the subject of many research studies." (PMID 27891156, 2016). "The observation that modified Brazil nut 2S albumin is still immunogenic while its allergenicity is reduced opens possibilities for developing immunotherapy for Brazil nut allergy." (PMID 24180644, 2013). "It was probable that the albumin used in this agent, which is produced locally in western countries, have exerted the antigenicity effect on the Chinese population leading to the allergic reaction." (PMID 23659317, 2013). "Although allergy and other adverse reactions to albumin-bound paclitaxel are far less common than with paclitaxel, the occurrence of peripheral neurotoxicity is uncommon but never as serious as in this patient, who could no longer walk." (PMID 39296984, 2024). "In the case of allergy to animal dander, especially for cat and dog allergy, natural allergen extracts that may contain albumin are used." (PMID 37928538, 2023). "In addition, in a recent hospitalization, he suffered a severe allergic reaction following intravenous administration of human albumin." (PMID 36851100, 2023). "Additionally, corticosteroid therapy, electrolyte fluid replacement, and albumin substitution are usually needed to resolve the allergic reaction." (PMID 36986665, 2023). "The involvement of ALB in allergy has been described in several studies." (PMID 34394070, 2021). "Secondly, due to evidence suggesting that cases of food allergy to amaranth exist, studies on amaranth allergy patients including skin-prick tests and oral challenges are required to make definitive conclusions about the allergenic potential of the albumin and globulin fractions from amaranth." (PMID 30897829, 2019). "Therefore, in our daily life, we should avoid adding oleic acid to egg or egg white in the pasteurization process, which may aggravate the allergy symptoms of egg albumin patients or egg allergy patients." (PMID 39856886, 2025). "In contrast to Gal d 5 (chicken serum albumin), which is a marker for secondary allergy to chicken meat after primary sensitisation to egg yolk or serum albumin carried by bird feathers (bird-egg or egg-bird syndrome), Gal d 7 is a marker for primary allergy to chicken meat." (PMID 40362486, 2025). "However, the immunological mechanisms of albumin sensitization have not yet been investigated in detail although this will be important for the development of allergen-specific prevention and allergen-specific immunotherapy (AIT) strategies for allergy to albumin." (PMID 37928538, 2023).
Allergy (continued). "Age, sex, smoking status, BMI, dust exposure, farm live, family allergy/asthma history, and cat ownership were demonstrated for the random sample and the asthma sample, including subsamples for those who were sensitized to lipocalins, albumin, and secretoglobin." (PMID 37632243, 2023). "Interestingly, the occurrence of severe reactions after peanut intake was correlated with 2S albumin allergy in northern Italy (ORc = 3.022 [95% CI = 1.3-6.8]; P = .007) and with LTP sensitization in Italy's center and south (ORc = 3.188 95% CI = 1.6-6.3]; P = .001)." (PMID 37780582, 2022). "However, the incidence of allergic reactions in PE may presumably be lowered by using human albumin solution instead of FFP, since allergic reactions are commonly associated with FFP, but very rarely with human albumin solution." (PMID 32899499, 2020). "Also, although rare, unnecessary use of human albumin may lead to allergy, complications, and side effects." (PMID 28979337, 2017). "Our study found that piglets with allergies had higher GLB and AP levels, and lower ALB levels, indicating that inflammation response enhanced and impaired intestinal function in the piglets." (PMID 39881721, 2024). "Pork-cat syndrome is a rare allergy condition in which patients allergic to cat dander also develop allergic reactions to pork and other mammalian meat products, such as BSA, due to cross-reactivity with serum albumin." (PMID 39036193, 2024). "Cases of a generalized allergic reaction or even shock symptoms have not yet been reported in connection with human serum albumin (HSA) in vaccines." (PMID 35729887, 2022). "Two patients experienced a suspected allergic reaction following the administration of 125I-human serum albumin and were not included in the study." (PMID 31138247, 2019). "The role of serum albumin in allergic diseases is complex and not fully elucidated." (PMID 40708118, 2025). "Using modern molecular allergy vaccines based on recombinant allergens, recombinant allergen derivatives or allergen-derived peptides will clearly be possible to eliminate the risk of inducing adaptive immunity to HSA by not including albumin and albumin-derived epitopes in the vaccines." (PMID 37928538, 2023). "This may occur as fever is a common AEFI with many vaccines but allergy-related AEFI occur more frequently with influenza vaccines due to the multiple antigens and the manufacturing process being in eggs with small amounts of egg albumin retained in influenza vaccines." (PMID 31675362, 2019). "Likewise, a Japanese investigation has observed that the serum albumin levels of asthmatic children are substantially lower than those of children without asthma, whereas the levels of children with wheezing symptoms or a history of allergic diseases are not significantly different." (PMID 38835754, 2024).
thrombosis (63 papers, 2013 to 2026). "Low levels of albumin are associated with an increased risk of mortality and thrombosis in patients with various conditions." (PMID 41438592, 2025). "A low ALB concentration is considered an integrative index for inflammation, hypercoagulability, or disease states that predispose patients to thrombosis." (PMID 38962086, 2024). "Previous studies have shown that cancer patients with lower serum ALB levels have a significantly increased risk of thrombosis and death compared to cancer patients with higher serum ALB levels." (PMID 38169674, 2023). "This study evaluated the association between serum albumin levels and preoperative deep vein thrombosis (DVT) in geriatric hip fractures." (PMID 37620804, 2023). "The study showed that ALB was less than 44.2 g/L, the risk of thrombosis increased approximately 2-fold." (PMID 38169674, 2023). "The results of our study indicated that anti-PLA2R antibody is superior to albumin and proteinuria in relation to the assessment of the risk of venous thrombosis in PMN." (PMID 35380081, 2022). "Many studies have revealed that serum albumin is inversely associated with artery and venous thrombosis events." (PMID 36077496, 2022). "The association between albumin levels and thrombosis occurrence in patients with cancer has been previously reported." (PMID 34521927, 2021). "Low serum albumin had significant association with deep vein thrombosis (OR = 1.99; p < 0.001) and pulmonary embolism (OR = 1.55; p = 0.011)." (PMID 31253199, 2019). "D-dimer and albumin have been individually associated with cancer-related thrombosis." (PMID 41156207, 2025). "It is generally believed that the albumin adheres to the surface of the materials can cause the formation of biological passivation film on the material surface, and inhibit the adhesion of platelets, thus preventing thrombosis." (PMID 39027361, 2024). "Through an in-depth analysis of deep learning and machine learning models in this study, it was discovered that certain variables, notably albumin levels and the type of locking solution used, play a pivotal role in predicting the risk of venous thrombosis associated with PICC." (PMID 39839389, 2024). "Furthermore, in multivariate logistic regression analysis, anti-PLA2R antibody was the independent risk factor for venous thrombosis, even adjusted for albumin and LDL." (PMID 35380081, 2022). "The present study reinforces and extends the results of an autoptic study indicating that thrombosis predisposes to poor survival; thus, on multivariable analysis, intra-hospital venous and arterial thrombotic events along with age and albumin were factors associated with death." (PMID 34218413, 2021). "Moreover, she had hypoproteinemia, and deep venous thrombosis (DVT) in both of her legs because of albumin loss and chronic consumption and long-time bed stay." (PMID 32569229, 2020). "A plethora of studies have extensively investigated the association between D-dimer and albumin with preoperative deep vein thrombosis (DVT)." (PMID 37653556, 2023). "Through Mendelian randomization analysis, the study further confirmed the relationship between low albumin levels and venous thrombosis." (PMID 41573392, 2025). "Comparison included blood tests [C-reactive protein (CRP), albumin, and D-dimer], the incidence of deep vein thrombosis (DVT), range of motion (ROM), and clinical scores before and 1 year after surgery." (PMID 37106430, 2023). "Although DAR is a novel combination in this study, it is established that D-dimer and albumin alone can serve as predictive factors for preoperative deep vein thrombosis (DVT) in hip fracture patients." (PMID 37653556, 2023). "The results showed that the incidence of DVT was 3.9% and in multifactorial analysis, D-dimer, albumin, blood glucose, time from injury to DUS, NLR, PHR, and AT III were identified as independent risk factors for thrombosis." (PMID 35396396, 2022).